ERBB2 (erb-b2 receptor tyrosine kinase 2)
Diseases named in the same sentence as ERBB2 in open-access papers (continued):
Sharing a sentence is not in itself a finding about the gene and the disease.
tumor (continued). "The expression levels of both genes are higher in the ERBB2+ (HER2+) and TNBC subtypes as compared to ER+ tumours (RH+)." (PMID 37452026, 2023). "We plotted the tumor volumes comparing the wildtype and the mice that received the vector, desARE3’UTR ERBB2-1, -3, and -30." (PMID 37359373, 2023). "Based on the results of this study, which showed a significant relationship between ERBB2, NRG4, and MIG6 and tumor characteristics, we further evaluated the predictive performance of these potential biomarkers." (PMID 37174100, 2023). "This study aimed to evaluate the relationship between serum ERBB2, NRG4, and MIG6 levels and tumor characteristics, overall survival, and tumor recurrence to determine the potential prognostic value of these signaling molecules for HCC." (PMID 37174100, 2023). "In terms of histopathology, BC tumours are primarily categorized based on the expression of receptors for progesterone (PR), oestrogen (ER) and ERBB2 (also known as Her2)." (PMID 37581480, 2023). "Studies have shown dual-targeting CAR-T cells MUC1 and ErbB2 were effective in killing MUC1+ and ErbB+ tumour cells, while sparing cells expressing only one of these antigens." (PMID 39935547, 2023). "As expected, co‐overexpression of PGAP3 and ERBB2 was also correlated with T stage (*p = 0.01), TNM stage (*p = 0.032), tumour size (*p = 0.032) and Lauren classification (**p = 0.008)." (PMID 37386793, 2023). "This suggests that signaling pathway genes co-opt both promoters, where tumor cells utilize signaling pathways differently via alternative promoter usage (for example in CDKN2A and ERBB2)." (PMID 37169774, 2023). "Subsequently, the CAR gene-laden DNA nanocomplex can be used to introduce ErbB2-targeted CAR, and the generated CAR-MΦs then act as “living” cures, thereby serially clearing the invasive tumor cells." (PMID 36805678, 2023). "All four members of this family, including HER1 (EGFR, ErbB1), HER2 (Neu, ErbB2), HER3 (ErbB3), and HER4 (ErbB4), play an important role in cell growth regulation, proliferation, and tumor migration." (PMID 39355049, 2023). "They act on targets such as IL-6, FOS, STAT3, ERBB2, and EGF, exerting effects on delaying tumor cell resistance and inhibiting tumor cell invasion and metastasis." (PMID 37990309, 2023). "Another possibility to evaluate HER2 status in CTCs is the detection of ERBB2 DNA amplification, mainly based on the use of FISH protocol specialized for CTCs to detect and map tumor cells in leukocyte background." (PMID 40028485, 2023). "The primary killing capacity by the ErbB2-redirected CD19 CAR T cells was as efficient as by the ErbB2 CAR T cells, however, adding CD19+ B cells furthermore reinforced the activation of the CD19 CAR T cells, thereby improving the anti-tumor activities." (PMID 36672182, 2023). "ERBB2, NRG4, and MIG6 serum levels were compared based on tumor characteristics, including BCLC stage, tumor-maximal diameter, and the number of tumors, using the Kruskal–Wallis test and bivariate (Spearman) correlation." (PMID 37174100, 2023). "Peptide-expanded populations of TILs recognizing either ERBB2 or MOB1A epitopes from two patient samples (OV777 and OV870) responded to matched tumor cells with IFNγ production." (PMID 36943460, 2023). "In the c-Neu (Erbb2/HER2) cancer models driven by the MMTV promoter, overexpression of the oncogene and tumor development is owned to promoter demethylation, an event that happens in early stages of development." (PMID 37269418, 2023). "Correspondingly, T cells with high affinity CARs recognized targets with low ErbB2 levels, whereas CAR T cells equipped with low affinity CARs were only activated by tumor cells with high ErbB2 levels." (PMID 38090558, 2023).
tumor (continued). "If a genetic alteration, such as ERBB2/Her2/neu or FGFR2 amplification, is homogeneously distributed uniformly across the tumor and its different clones, a single tumor-cell-bearing biopsy would be sufficient to reliably document this genetic alteration." (PMID 36416959, 2023). "In addition, EGFR exon 20 insertions, Erb-B2 receptor tyrosine kinase 2 (ERBB2) mutations, neuregulin 1 (NRG1) fusions, KRAS proto-oncogene (KRAS) G12C, and tumor mutational burden (TMB) are evolving targeting/biomarkers and may eventually be included in the test panels, if possible." (PMID 37371816, 2023). "The results of an in vitro tumor spheroidization assay showed that the PPARγ antagonists GW9662 and T0070907 reduced tumor spheroids formation in ERBB2-positive cells." (PMID 37251321, 2023). "TCGA portal analysis revealed that ERBB2 expression was significantly up-regulated in HCC tumor tissues compared to normal tissues, and the expression levels varied across different tumor grades and stages." (PMID 37324014, 2023). "In NSCLC, EREG reduces TKI-induced apoptosis through the EGFR/ERBB2 and AKT signaling pathways, thereby contributing to TKI resistance in tumor cells." (PMID 37091977, 2023). "In 36% of the ERBB2 low CN metastatic samples, we observed a low expression of ESR1, even though their primary tumor was ER+ and as such, endocrine therapy was received." (PMID 37968696, 2023). "The gene encoding the approved CAR target ERBB2 was expressed more highly in matched normal tissue than in tumor tissue, indicating that the new targets uncovered herewith may possess greater tumor-vs-nontumor stratification abilities than at least one of two established HNSC CAR targets." (PMID 37835579, 2023). "This signature, together with high expression of ERBB2 and co-amplified CDK12 in organoids, recapitulated the genomic changes from the patient’s original tumor." (PMID 37508518, 2023). "Eshhar and his team engineered two functional “first generation” CARs targeting antigens native to tumor cells: the alpha folate receptor and HER2 (ERBB2)." (PMID 38006053, 2023). "In the present study, we revealed that serum ERBB2 and neuregulin 4 (NGR4) are independent prognostic factors for survival and tumor recurrence and suggested a possible synergistic effect between these two prognostic factors." (PMID 37174100, 2023). "For these tumour types, therapies targeting EGFR, ERBB2, or their downstream effectors such as MEK or PI3K have shown some degree of success." (PMID 38041118, 2023). "Next, we studied the complete blood chemistry of the tumor-bearing control mice and those receiving desARE3’UTR ERBB2-1, -3, and -30." (PMID 37359373, 2023). "For the cirReNET we built, there were many targeted genes involved in the mechanism of tumor genesis, such as AKT1, ErbB2, ITGB7, BAX, MAPK, FBXL12, CCL7 and so on." (PMID 35611168, 2022). "We first compared the expression pattern of EGFR, ERBB2, ERBB3, ERBB4 in CESC tumor and normal tissues." (PMID 35581263, 2022). "Combining tumor-normal and inter-tumor analyses, we identified overexpressed targets including PDGFRB, FGFR4, ERBB2/3, CDK6 kinases and MFAP5, HMCN1, and Hsp proteins in HCC, many of which showed low frequencies of genomic and/or transcriptomic aberrations." (PMID 35433463, 2022). "In orthogonal comparisons of ERBB2 (HER2) amplification and MSI calls made by LiquidHALLMARK against FISH and fragment size analysis using patient-matched tumor tissue samples, a PPA of 66.67% and 80.00% respectively was demonstrated." (PMID 35486650, 2022). "By analyzing FFPE-DNA from tumor specimens with ddPCR, ERBB2 amplification was found in 7/28 (25%) patients; 5 in HER2 3+, 1 in HER2 2+, and 1 in HER2 0–1+." (PMID 35565309, 2022). "The inspected biological process category showed positive regulation of viral transcription, apoptotic signaling, ERBB2 signaling, chemotaxis of immune cells, and ERK1 and ERK2 cascade, which has tumor-promoting effects in HCC." (PMID 35057034, 2022).
tumor (continued). "The gene expression levels of Erb-B2 receptor tyrosine kinase 2 (ERBB2) and MKI67 from Select-seq were in agreement with the corresponding RNA in situ hybridization results in serial sections of the same tumour." (PMID 35534484, 2022). "The result of tumor immune infiltration showed that AR was positively correlated with CD4+ T cells, macrophages, and dendritic cells, while ERBB2 was negatively correlated with CD8+ T cells, macrophages, neutrophils, and dendritic cells." (PMID 35069767, 2022). "The proliferative type is mainly characterized by excessive activation of cell proliferation-related signaling pathways such as RAS/MAPK, MET, EGFR, ERBB2, and NOTCH; therefore, the tumor is more aggressive." (PMID 36578029, 2022). "We initially profiled the expression pattern of ERBB2 and ATM mRNA levels in a panel of different normal and tumour tissues with bioinformatics analyses using the TCGA database (Cohort one)." (PMID 36056635, 2022). "The results showed that increased CDC42, CDH2, ERBB2, JAG1, YAP1, and YWHAZ were found in the tumor tissues." (PMID 35340237, 2022). "The co-amplification of ERBB2 and TOP2A was assessed by shallow whole genome sequencing on tumor tissue whenever available." (PMID 35565244, 2022). "Well-known tumor-related genes were found in this ranking, such as ERBB3 (24th rank), VEGFA (75th rank), and ERBB2 (365th rank)." (PMID 35626066, 2022). "Ep5 from a luminal-HER2-type tumor showed a luminal-specific pattern of gene activity (KRT8/18) as well as greater ERBB2, GRB7, and MYC activities, which are often coamplified in breast cancer." (PMID 35676392, 2022). "In an attempt to elucidate the molecular mechanism (s) by which ERK3 overexpression promotes tumor development, we examined the effects of ERK3 overexpression on the activating phosphorylations of ERBB1, ERBB2, and ERBB3." (PMID 34719109, 2022). "Sufficient tumor material was available from fourteen patients treated with certolizumab (14/18; 78%) for EGFR, KRAS, BRAF, ERBB2, and ALK testing and from ten patients (10/18; 56%) for NGS." (PMID 36241629, 2022). "In contrast, HER2/ErbB2 suppression inhibited HSF-1, which led to blocking of Hsp90alpha chaperoning activity and tumor growth." (PMID 35887137, 2022). "Remains to be clarified the heterogeneity in HER2/ERBB2 assessment in clinical trials and even across different tumor types." (PMID 36013315, 2022). "Three P-values of the KICH group revealed that tumor proliferation, the extracellular matrix (ECM)-related gene, and degradation of ECM possessed a more prominent advantage in ERBB2 mutant cancer and progression-free survival." (PMID 36172165, 2022). "Following the assessment of ddPCR performance for ERBB2 detection, FFPE-DNA isolated from the tumor surgical specimens and cfDNA samples collected immediately before surgery from the 28 prospective patients were analyzed." (PMID 35565309, 2022). "We and others have demonstrated that PTPRO is capable of dephosphorylating RTKs such as ERBB2 and EPH receptors and repressing tumor growth." (PMID 35431974, 2022). "The downstream signaling pathways, such as tumor proliferation, ECM-related genes, and degradation of ECM, are involved in ERBB2 gene demethylation and immune activation in cancer progression." (PMID 36172165, 2022). "If similar findings are confirmed across tumor type, discovering tissue ERBB2 CNG by NGS can facilitate clinical trial enrollment and utilization of HER2-thearpy in diseases for which HER2 testing by IHC/FISH is not standard." (PMID 35126865, 2022). "Half of the tumors (50%) carried at least one molecular alteration that is targetable in other tumor types, including alterations in CDKN2A (6.0% biallelically inactivated), ERBB2 (9.3%) and PIK3CA (10%)." (PMID 36335173, 2022).
tumor (continued). "Tumours that harbour both HER2-E and ERBB2-high are classified as “HER2-addicted” tumours and, therefore, are considered the most sensitive tumours to anti-HER2-targeted therapies." (PMID 35158778, 2022). "ERBB2 and RAF1 were altered in 37% and 45% of G3pT1 tumours, respectively, but only in 5% and 10% of G1pTa tumours, respectively." (PMID 35655252, 2022). "Human epidermal growth factor receptor 2 (HER2 or ERBB2) is a member of the epidermal growth factor receptor family, involved in the regulation of tumor cell proliferation, apoptosis, adhesion, migration, and differentiation." (PMID 35186729, 2022). "According to their results, the dual targeting of CARs promoted the growth of CAR T-cells while effectively killing tumor cells co-expressing MUC1 and ErbB2." (PMID 35883508, 2022). "The genomic landscape of RMS further includes genetic aberrations in FGFR4, IGF1R, PDGFRA, ERBB2/4, MET, MDM2, CDK4, and PIK3CA and BCOR providing targets for molecular therapies for this tumor type." (PMID 34073340, 2021). "Secondly, as a tumor suppressor, FOXP3 represses many key target genes in cancer development and progression, such as HER2/ERBB2, BRCA1, SKP2, and CD44, providing a strong link between FOXP3 and cell cycle regulation as well as FOXP3 and DNA repair system." (PMID 34768829, 2021). "And assessment of ErbB2 expression is helpful in differential diagnosis of HCC and other tumor infiltrates in liver tissue." (PMID 32591879, 2021). "Here, we use a CRE-activated HER2 orthologue to specifically target HER2/ERBB2 oncogenic activity to basal or luminal ER− mammary epithelial cells and perform a detailed analysis of the tumours that develop." (PMID 34003256, 2021). "First, second and third generation CAR NK cells have been generated, using lentiviral vectors, to target tumor antigens such as CD19, CD20, CD33, CD7, CD22, ErbB2 and EGFR." (PMID 33450862, 2021). "Neuropilin 1 (NRP1) as a coreceptor of growth factors is involved in tumor progression that affects tumor cell viability through EGFR and ErbB2 signaling pathways." (PMID 33827418, 2021). "In multivariable analyses that included STRAT4 mRNA measurements, tumor size, nodal status, PGR, ERBB2, and MKi67 were independent prognostic factors for time to DR." (PMID 34371382, 2021). "Research in BC showed that GRB2 is a pivotal molecule in tumor growth and downregulation of its expression can lead to inhibition of breast cells with high EGFR and ERBB2 expression levels." (PMID 34679042, 2021). "In cervical cancer, GDF15 which belongs to TGF-β superfamily phosphorylated PI3K/AKT and MAPK/ERK signaling pathways via ErbB2, a member of EGFR family, to achieve the purpose of promoting tumor progression." (PMID 34717710, 2021). "As the overall expression across all tumours and subtypes revealed differences for KRT20, ERBB2, and ESR1 mRNA expression, the potential predictive value of the target gene expression of KRT20, ERBB2, and ESR1 was further analysed by partitioning test." (PMID 34073233, 2021). "A recent study in PgR-low/null tumors defined phospho-PgR target gene sets (ERBB2, PAX2, AHR, AR, and RUNX2) which regulate cancer stem cell biology and increase tumor heterogeneity." (PMID 34638241, 2021). "The tumor expression levels of receptor tyrosine kinase genes, including VEGFR-1, VEGFR-2, PDGFR-α, PDGFR-β, ALK, EGFR, ErbB2, and B-RAF, were analyzed." (PMID 33764261, 2021). "Integrin β4 participates in multiple signaling pathways and can also enhance them, including ErbB2, PI3K, FAK/AKT, and c-Met, to promote tumor progression." (PMID 34439865, 2021). "EGFR and ErbB2 are often over-expressed in HNC cells and are frequently prone to heterodimerization that confers tumor growth advantage." (PMID 34561494, 2021). "Duplications in ERBB2 (also called HER2) and deletions in PTEN or MAP2k4 were also noted in tumor genome." (PMID 34065872, 2021).
tumor (continued). "In silico analysis of transcriptional data from TCGA datasets (PanCancer Atlas) derived from cancer patients shows that HER2 (ERBB2) and B7H6 (NCR3LG1) transcripts are expressed in different tumor entities." (PMID 35036073, 2021). "Western blot analyses showed that infigratinib-resistant HCC21-0208, HCC06-0606, and HCC01-0909 tumours constitutively express higher levels of p-EGFR, p-ErbB2, and p-ErbB3." (PMID 34156519, 2021). "In the present study, 22 paired tumor and non-tumor normal tissue were examined for mRNA expressions of MET and ERBB2." (PMID 34335943, 2021). "The first tumor, PS13-9062, was a grade 3 ER+, PR+, and ERBB2- (pT2, pN0) arising in a patient with a germ line BRCA2 mutation." (PMID 34011996, 2021). "Generally, an upward trend was observed in the mRNA levels of total EGFR, ErbB2, and ErbB3 from the PDX tumours treated with infigratinib." (PMID 34156519, 2021). "We used cBioPortal portal to investigate correlations between the mRNA levels of ERBB2 and the EMT markers in each tumor sample." (PMID 34575017, 2021). "Despite such insignificant results in the expression level of ErbB2 between INT and IT groups, tumor size in the INT group continued to increase from the baseline, and the tumor growth rate was higher than that in the IT group." (PMID 34164110, 2021). "To further confirm that this anti-angiogenic effect is related to the expression of p32 on TDEC and tumor vasculature, we engineered GBM83 cells to overexpress ErbB2." (PMID 34127674, 2021). "In line with this, targeting the pathways closely upstream or downstream of Shc1 (e.g., ErbB2, EGFR, MEK, ERK, PTEN, PI3K) by drugs or molecular manipulation has been shown to enhance anti-tumor immune responses in various studies, as discussed later." (PMID 33807608, 2021). "A previous study displayed that NRG1 exerted its roles in tumors by binding to ERBB2 or ERBB3, resulting in tumor cell proliferation, invasion, and migration." (PMID 34531912, 2021). "Formalin-fixed paraffin-embedded tumour tissue samples from TUR-BT of 54 patients (42 males, 12 females, median age of 64) with MIBC were analyzed for KRT20, KRT5, ESR1, and ERBB2 mRNA expression." (PMID 34073233, 2021). "Repeated tumor biopsy for further immunohistochemistry showed all mismatch repair proteins stable, a PD-L1 combined positive score (CPS) of 2, and an ERBB2 expression." (PMID 34367146, 2021). "In contrast to ERBB2 inhibition, over-expression of ERBB2 in the normal-like ERBB2-negative MCF-10A and MCF-7 tumor line led to increased abundance of phosphorylated ZFP3/ZFP36/TTP protein." (PMID 34535639, 2021). "Similar to our findings in primary UC tumor samples, EGFR and ERbB2 phosphorylation was observed in all cell lines." (PMID 34600548, 2021). "ROC curves showed 75%, 75%, and 69% sensitivity and 88%, 81%, and 81% specificity for distinguishing neoplasia from normal for EGFR, claudin-1, and ErbB2, respectively." (PMID 36345439, 2020). "Copy number alterations were retained across several tumor-organoid pairs include CDKN2A, ERBB2, NF1, and SNX31." (PMID 32774159, 2020).